RN7SL44P (RNA, 7SL, cytoplasmic 44, pseudogene)
Gene: Miscellaneous RNA gene on chromosome 1 (153,500,463 to 153,500,764, reverse strand). Ensembl gene ENSG00000263841.
Homologues: Orthologues: chimpanzee Metazoa_SRP (99% identical), macaque Metazoa_SRP (92% identical). Paralogues in human: RN7SL1 (85% identical), RN7SL2 (85% identical), RN7SL3 (83% identical), RN7SL451P (82% identical), RN7SL444P (82% identical), RN7SL296P (82% identical), RN7SL147P (81% identical), RN7SL220P (81% identical), RN7SL408P (81% identical), RN7SL650P (81% identical), RN7SL664P (81% identical), RN7SL575P (81% identical), and 703 more.